NANOG (Nanog homeobox)
Diseases named in the same sentence as NANOG in open-access papers (continued):
Sharing a sentence is not in itself a finding about the gene and the disease.
cancer (continued). "Nuclear NFAT transcriptionally activates the expression of several genes including NANOG, OCT4, SOX2, and FGF19 which are involved in cancer cell stemness." (PMID 35711942, 2022). "The expression of the stemness-associated markers OCT4, SOX2, NANOG, KFL4 and c-MYC by LA at the mRNA and protein level, and the unique expression patterns suggest a putative presence of CSC subpopulations within LA, which may be a novel therapeutic target for this cancer." (PMID 34685477, 2021). "Results demonstrate that the extract, at IC50 doses, was able to significantly decrease the expression of CD44, CD24, NANOG, SOX-2, and OCT-4, indicating a reduction in the amount of cancer stem cells (CSCs) in the culture." (PMID 33572111, 2021). "Stemness-related factors OCT4, SOX2, NANOG, and KLF4 are common transcriptional regulators in cancer stem cells." (PMID 33436575, 2021). "Further, treatment with EC359 reduced the spheroid formation of EC cancer stem cells and reduced the levels of cancer stem cell markers SOX2, OCT4, NANOG, and Axin2." (PMID 34400617, 2021). "STAT3 is also involved by enhancing the acquisition of EMT and cancer stem cells traits by CRC cells, through transcriptional induction of NANOG TF." (PMID 34440220, 2021). "The potential regulatory effects of DUXAP8 on the expression of the cancer stem cell marker, CD133, and stem cell-related genes, including OCT4, NANOG, and Sox2 were then investigated." (PMID 34957112, 2021). "The increased expression of self-renewal regulatory factors important in cell pluripotent state such as OCT4, NANOG and SOX2 was detected in various types of cancers." (PMID 33471801, 2021). "Consistently, FBP1 overexpression obviously inhibited the expression of SOX2, OCT4, and NANOG, which regulated CSC-like property in various cancers." (PMID 34363022, 2021). "The core regulatory network for embryonic stem cell maintenance and self-renewal OCT4, SOX2, KLF4, NANOG, and SALL4 are abnormally expressed in human tumor samples suggesting the presence of cancer stem cells." (PMID 34249759, 2021). "The expression levels of cancer stem cell marker proteins ALDH1A1, C‐Myc, OCT4, NANOG, KLF 4 and SOX2 were found to be significantly higher in MCF‐7‐CSC than those in MCF‐7." (PMID 33305893, 2021). "We also found strong correlations between MES and ADRN TFs with markers of cancer cell stemness and cancer cell motility including CDH1, CDH2, NANOG, SOX2, TWIST1, VIMENTIN, and Fibronectin across cancers." (PMID 35201514, 2021). "POLβ knockdown cells had a significant increase in NANOG, SOX2, C-MYC and OCT4 which are well-known markers of cancer stem cells." (PMID 34406589, 2021). "IGF-1 treatment induced the expression of NANOG and OCT4 and sphere formation in HepG2.2.15, Hep3B, and PLC5 cell lines, and inhibition of IGF-1R by shIGF-1R suppressed cancer stemness properties in these cell lines." (PMID 33669204, 2021). "Nuclear PKM2 binding to Oct4 can upregulate cancer stemness-related genes (CD133, CD44, LDHA, NANOG), thus promoting the CSCs population’s enrichment from several human cancer types." (PMID 33828530, 2021). "As this phenotype is one of a characteristic of cancer stem cells (CSCs), stemness-related markers were tested: OCT-3/4, NANOG, SOX2, and ALDH1." (PMID 35127467, 2021). "The FOXM1 transcriptional network includes pluripotency genes, such as SOX2, NANOG, and OCT4, in several cancer models." (PMID 34205406, 2021). "Meanwhile, PC-9/GR/sh-BTK cells exhibited significantly lower levels of cancer stemness markers such as KLF4, SOX2, NANOG, and CD133, than its counterparts, whereas the pBTK-N1 cells expressed the highest levels of these markers." (PMID 34315851, 2021). "Pluripotency genes, POU5F1 and NANOG, displayed approximately 2–3 fold increases in their protein expression in HT29 cells grown on colorectal PDS compared to 2D, whereas other cancer stem cell markers, such as CD44 decrease by approximately 90%." (PMID 33356003, 2021).
cancer (continued). "The presented data suggest that RASSF1C expression and its downstream Rho/ROCK/pMLCII pathway upregulation re‐wire cells to express cancer stemness markers such as CD133, ALDH1, NANOG, and OCT4." (PMID 34532864, 2021). "We previously illustrated that high expression of IGF-1R correlates with expression of cancer stemness markers (OCT4 and NANOG) and early recurrence and with sorafenib resistance properties in HCC." (PMID 34359714, 2021). "Enrichment of cancer stem‐like cells was confirmed by investigating the expression of SOX2, KLF4, NANOG and OCT4 key stemness genes using real‐time PCR." (PMID 33634564, 2021). "To confirm the tumorsphere formation, we isolated RNA from sphere and analyzed cancer stem cell markers, SOX2, OCT4, and NANOG using real-time PCR." (PMID 33925065, 2021). "In the meantime, SPP1 overexpression promotes the expression of KLF4, NANOG, SOX2, and BMI1, which were cancer stem cell markers." (PMID 33996808, 2021). "Using both over‐expression experiments and epigenetic editing, here we show that RASSF1C drives expression of cancer stemness features in amoeboid invasive cells and upregulates a panel of cancer stem cell markers, such as ALDH1, CD133, and NANOG." (PMID 34532864, 2021). "To verify that the spheres in our setup were enriched in cancer stem cells, we tested the expression of the stemness-related transcription factors POU5F1 (Oct4), SOX2, CD44, PROM1 (CD133), and NANOG in spheres and adherent cells 72 h after seeding." (PMID 34832951, 2021). "Our results show that CEBPD can directly bind to the SOX2, OCT4, NANOG, and ABCA1 promoter regions to promote the properties of cancer stemness and drug resistance." (PMID 33436575, 2021). "IGF/IGF-1R signaling has been reported to induce the expression of cancer stemness-related transcription factors, including IGF-1R, NANOG, OCT4, NFκB, STATs, SOX2, and YAP." (PMID 33669204, 2021). "Consistent with the role of TGFβ in controlling cancer stemness, NS1643 also produced a strong inhibition of NANOG, SOX2, and OCT4 while arresting the cell cycle in G0/G1." (PMID 34885136, 2021). "NANOG is also a pluripotency/CSC regulatory factor, found to be widely detected in multiple cancers, enriched in tumor cells that exhibit stem cell-like properties and with important prognostic implications in several cancer types, including OSCC." (PMID 34201050, 2021). "Other groups have illustrated that the expression of cancer stemness genes (OCT4, NANOG) induced by elevation of IGF-1/IGF-1R, correlates with high tumor recurrence in HCC patients and sorafenib resistance." (PMID 33669204, 2021). "The gene expression of CRC cancer stem cell markers, including SOX2, OCT4, NANOG, KLF4, ALDH1A1, and CD44, were all highly expressed in CARMA3-overexpressed cells compared to control cells." (PMID 34885061, 2021). "It was recently found that the replication of HBV is positively correlated to the expression of cancer stemness markers (EpCAM, CD44, CD133, NANOG, OCT4, and Sox2), tumorigenesis, and self-renewal." (PMID 33669204, 2021). "The regulation of NANOG and OCT4 in HCC cancer stem cells by IGF/IGF-1R signaling was elucidated in HCC cell lines." (PMID 33669204, 2021). "Furthermore, cisplatin treatment of CAFs caused a negative association of colony area with BIRC5 and EGF, and a positive association of colony area with NANOG expression in cancer cells treated by CMCAF_post-cisplatin medium, which was not seen in CMCAF cocultured cells." (PMID 33671869, 2021). "The effects of combination of DSF and Galunisertib on the self-renewal ability, the expression of cancer stem cell markers (such as CD133, SOX2, and NANOG), and the ability for differentiation into multiple cell types are necessary." (PMID 34638842, 2021).
cancer (continued). "However, our results indicate that miRNAs and lncRNAs, particularly miR-145 and RoR, might be among important regulatory mechanisms of NANOG in dysplasia and cancer development of oral cavity, indicating their potential role as biomarkers and therapeutic targets." (PMID 33643897, 2020). "PC CM also increased NANOG expression in HCT116 cells (P = 0.0002), a transcription factor essential for stemness which is expressed in multiple cancers, including CRC." (PMID 32767843, 2020). "The in vivo administration of EGCG also shows the reduction of cancer growth and the levels of stemness factors, such as SRY-box transcription factor 2 (SOX2), Octamer-binding protein 4 (OCT4), and Nanog homeobox (NANOG)." (PMID 33066509, 2020). "Since we found that USP38 suppressed mRNA levels of cancer stem cell related genes, we next analyzed the mRNA half-life of CD133, SOX2, and NANOG to gain further insights into USP38 mediated regulation of gene transcripts." (PMID 32404892, 2020). "This includes OCT4 protein expression, POU5F1, NANOG and SOX2 gene expression in cell lines or cancer-initiating cells." (PMID 32664372, 2020). "The pluripotency factors NANOG, SOX2, and OCT4 have been reported as CSC markers and key regulators in HNSCC and other cancers." (PMID 32635524, 2020). "ZIC2, as transcription factor (TF), behaved as the other core pluripotent TFs (SOX2, NANOG, c-MYC) in cancer stem cells." (PMID 32922547, 2020). "Our results also showed that the expression of cancer stem cell marker genes (e.g., MYC, NANOG, OCT4, and KLF4) was higher in C4-2B cells than that in LNCaP cells and it was markedly decreased by the silencing of SETD1A." (PMID 32629770, 2020). "There is a direct relationship between the expression of OCT4B1 and stemness-related genes (OCT4, SOX2, NANOG, and KLF4), and its downregulation in cancer cell lines inhibits the expression of these genes[24 ▶]." (PMID 32429647, 2020). "The levels of cancer stemness-related genes (ABCG2, BMI1, NANOG, KLF4, and OCT4) mRNA and proteins (ABCG2, Oct4, Bmi-1, and CD44) expression were downregulated with treatment of STF-31 in HBx-expressing MHCC-97H cells." (PMID 32168902, 2020). "Expression levels of cancer stem cell markers (CD44, CD133, SOX2, OCT3/4, and NANOG) were also decreased after silencing of SKIL in CALU-3 and NCI-H520." (PMID 33268765, 2020). "This, in turn, induces expression of core stem cell genes NANOG, SOX2 and POU5F1, leading to increased cancer stemness and tumorigenic potential." (PMID 32235004, 2020). "Inhibition of HSP90A with AUY922 robustly dampened AKT phosphorylation level and expression of the effectors in NANOG signaling, such as MCL-1, Cyclin A, and TCL1A across all tested cancer cells." (PMID 31992715, 2020). "Although to a much lower extent than regular NANOG, expression of the human-specific NANOGP8 retrogene, often expressed in human cancers, was also slightly induced by the reprograming process in a STAT3-dependent manner." (PMID 32580970, 2020). "We observed a positive correlation between NANOG and HSP90A protein levels in a variety of human cancer cells." (PMID 31992715, 2020). "IL-22 activates the STAT3 phosphorylation cascade in cancer cells and induces the expression of stem cell markers (SOX2, NANOG, and POU5F1), resulting in increased cancer stemness and tumorigenic potential." (PMID 32670290, 2020). "Homeobox transcription factor and embryonic stemness (ES) gene NANOG, along with its pseudogene NANOGP8, have critical roles in cancer stem cell (CSC) maintenance, tumor progression, cancer recurrence, metastasis, and therapy resistance." (PMID 33137926, 2020). "SOX2 and OCT4, along with other induced pluripotent stem cell markers KLF4, NANOG, and c-MYC, regulate stemness in CSCs and have been used them to characterize CSCs in other cancer types." (PMID 33147716, 2020).
cancer (continued). "The expression of ALDH1A1, a CSC marker, and the cancer stemness factors including BMI1, NANOG, and octamer-binding transcription factor (OCT4) were also reduced in both AN3CA and HEC1A cells after TRIB3 silencing." (PMID 33334065, 2020). "Another NANOG regulator, AGR2, is involved in tumorigenesis and progression of multiple human cancers." (PMID 32733958, 2020). "Several transcription factors, including BMI1, LGR5, NANOG, OCT4, and SOX2, are upregulated in various cancer types and promote stemness maintenance, local tumor invasion, and distant metastasis." (PMID 30866999, 2019). "CAFs play a critical role in the tumor niche, where CSCs maintain high tumorigenicity and cancer stemness with significantly high expression of OCT4 and NANOG." (PMID 31505803, 2019). "NANOG is a direct FRA1 target gene likely to play a central role in conferring increased stemness and malignancy to the cancer cell." (PMID 30804456, 2019). "In cancer stem cells, many transcription factors, especially OCT4, NANOG, and SOX2, are overexpressed, a pattern common to that in early embryonic stem cells." (PMID 31375149, 2019). "The cancer stemness properties are governed by many oncogenic pathways such as STAT3, NOTCH, WNT, and NANOG, which are highly dysregulated in CSCs due to genetic changes." (PMID 30709346, 2019). "In these primary non-cancerous cells, ML-60218 inhibited pre-tRNATyr by 40%, comparable to the matched cancer cells (36% inhibition), but had minimal effect on DR2 Alu, NANOG, CK8 or CK14 expression." (PMID 30820548, 2019). "NANOG and OCT4 protein levels were decreased in RPSAP52-depleted cells, suggesting this lncRNA promotes features of cancer stem cells." (PMID 31484926, 2019). "Tumor growth and the mRNA expression of lncRNA AB209630, miR373, EphB2, and NANOG evaluated in dissected tumor tissue by real-time PCR, the CD133+ cancer stem cells were isolated by flow cytometer, and the changes of the tumor sphere forming were measured." (PMID 31147453, 2019). "It has been reported that pluripotent cancer cells with microRNA-302s transfection exhibit decreased tumorigenicity, genomic demethylation, and elevated expressions of SSEA-3/4, SOX2, NANOG, and Oct-3/4." (PMID 31464654, 2019). "Further analysis of exosomal DNA sequences of NANOG and other embryonic stemness genes (OCT3/4, SOX2, etc.)may establish a robust collection of exosome based diagnostic markers, and further elucidate the mechanisms of cancer formation, progression, and metastasis." (PMID 29787607, 2018). "On co-treatment, cancer stem cell genes (OCT4, SOX2 and NANOG) were found to be down-regulated, which indicated the elimination of the NB-cancer stem cell properties." (PMID 29774131, 2018). "By determining the optimal cut-off using ROC curves for each molecule, the individual sensitivity and specificity of these six molecules (NANOG, CD49f, LGR5, ΔNp63, SOX2, and CD24) for cancer detection ranged from 29.2% to 62.5% and 83.3 to 100%, respectively." (PMID 30327565, 2018). "To conclude, we analyzed the influence of CPEB1 on cancer stemness in HCC cells by analyzing self-renewal ability, chemoresistance, metastasis and expression of the stem cell-related genes OCT4, NANOG, SOX2, LIN28, CD24, EpCAM and CD133." (PMID 30237545, 2018). "More investigations showed higher level of stem cell (NANOG, OCT4, SOX2) and cancer stem cell (CD44 and ALDH1) markers in BORIS-positive cells in comparition to BORIS-negative cancer cells." (PMID 30323717, 2018). "A Cancer Stem Cell Transcription Factor Activation Array (Signosis, Inc, number FA-1004) also found KLF4, MYC, NANOG, OCT-3/4, SOX-2 and SNAIL activated in both MCF-7 and T47D after treatment with the CM of HA-BrC cells (data not shown)." (PMID 29928478, 2018). "NANOG has been demonstrated to play an essential role in the maintenance of embryonic stem cells, and its pseudogene, NANOGP8, is suggested to promote the cancer stem cell phenotype." (PMID 29787607, 2018).
cancer (continued). "This implies that through OCT4, KLF4, NANOG, and SOX2 alteration, KRT19 regulates cancer stem cell reprogramming efficiency in KU-CSLCs." (PMID 29747452, 2018). "Leptin also induces the expression of TFs associated with the maintenance of the cancer stem cell phenotype, such as NANOG, SOX2, and OCT4 in a STAT3-dependent manner, promoting a more aggressive phenotype of cancer cells." (PMID 30404206, 2018). "Results of “ChEA 2016” analysis for 96 ≪stemness genes≫ showing elevated expression in TAMRA+ Krebs-2 carcinoma cells relative to TAMRA− cells, with regard to enrichment with SOX2/OCT4/POU5F1/NANOG/KLF4/c-MYC binding sites." (PMID 30505319, 2018). "In RCC, ALDHhigh subpopulation as assessed by the Aldefluor assay has been shown to be the cancer stem cells population, which has upregulated levels of OCT-4 and NANOG." (PMID 29162985, 2017). "Collectively, besides its ability to confer anti-apoptotic property to cancer cells, API5 is also able to turn tumor cells into CSC-like cells by regulating NANOG expression." (PMID 28092370, 2017). "We also detected upregulation of genes involved in cancer metastasis and cancer stemness (FOXC2, SNAI2, CXCRs, and IGF1), cell stemness (NANOG, POU5F1, and KLF4), metalloproteinases (MMP7, MMP10, and MMP13), and angiogenic factors (IL-8 and S1PR1)." (PMID 28423353, 2017). "The expression levels of stemness genes as OCT4, NANOG, and CD133 decreased in the cancer cells on both CS and CSHA membranes with IWP-4 treatment." (PMID 28367998, 2017). "There are several TFs, such as EGF1, HIF1A, the E2F family and NANOG, that play different regulatory roles in tumor cells, and it is also known that SP1 expression levels are higher in cancer cell lines than in normal cells." (PMID 28531296, 2017). "As expected, the phosphorylated states of STAT3 were markedly inhibited by WP1066 and S3 l-201, so as the cancer stem cell markers Nestin, SSES-1, and NANOG." (PMID 29284440, 2017). "Transcription of NANOG, one of a pluripotency factor, is known to be located downstream of GLI and activated by GLI proteins in several cancer models." (PMID 28245563, 2017). "Our studies suggested a potential alternative strategy of inhibiting the NANOG pathway by blocking the gene expression of a more specific component of the NANOG pathway, NANOGP8, in cancer cells." (PMID 28453235, 2017). "Accordingly, we next looked at a potential relationship between 14q32 miRNAs expression and cancer stem cell markers, and we examined the expression of CD44, ABCG2, ALDH1A1, NANOG and c-MYC genes in 53 tumor samples." (PMID 27980227, 2017). "Altogether, cisplatin enriches cancer stem cells properties in SP fraction, which is evident from increased levels of pluripotency gene OCT4/SOX2/NANOG expression." (PMID 29169370, 2017). "PRI-2191, PRI-1907 and PRI-1917 downregulated the expression of NANOG, OCT3/4 and SOX2, i.e., pluripotent stem cell-related genes involved in the stem cell renewal, which are aberrantly overexpressed in several cancers." (PMID 27314328, 2016). "Hypoxia can induce stem cell markers such as octamer-binding transcription factor 4 (OCT4), NANOG, SOX2, kruppel-like factor 4 (KLF4), c-MYC, and microRNA-302 in 11 cancer cell lines including HCC cells through hypoxia-inducible factor (HIF)." (PMID 27050147, 2016). "MCF7/C6 cells are with enrichment of cancer stem-cell like cells with positive staining of CD44+/CD24-/low, OCT3/4 and NANOG." (PMID 27036550, 2016). "The Cancer Atlas feature was interrogated to assess the antibody staining of YY1, SOX2, OCT4, NANOG and BMI1 in different cancer types." (PMID 27225481, 2016). "The results showed a trend of increasing NANOG1 expression from sphere cells to adherent cancer cells to GES-1 cells, and a trend of increasing NANOG/P8 expression from sphere cells to GES-1 cells to adherent cancer cells." (PMID 28033430, 2016).